ZNF821 (zinc finger protein 821)
Description:
May be involved in transcriptional regulation.
Tractability: No criterion of Open Targets' tractability assessment is met for any kind of drug.
Gene: Protein-coding gene on chromosome 16 (71,859,680 to 71,895,336, reverse strand). Ensembl gene ENSG00000102984.
Subcellular location: Nucleus
Subcellular location (Human Protein Atlas): Nuclear speckles; Nucleoplasm
Gene Ontology:
Molecular function: protein binding; sequence-specific double-stranded DNA binding; DNA-binding transcription factor activity; RNA polymerase II cis-regulatory region sequence-specific DNA binding
Biological process: regulation of transcription by RNA polymerase II
Cellular component: nuclear speck; nucleus
Genetic constraint (gnomAD): Loss-of-function variants: 16 observed, 46.32 expected, observed/expected ratio (o/e) 0.35, 90% interval 0.23 to 0.52. The upper end of that interval is the gene's LOEUF score, 0.52, which puts it in group 2 of 6, group 1 being the genes least tolerant of losing a copy. Missense variants: 436 observed, 570.36 expected, observed/expected ratio (o/e) 0.76, 90% interval 0.71 to 0.83. Synonymous variants: 204 observed, 208.26 expected, observed/expected ratio (o/e) 0.98, 90% interval 0.87 to 1.1.
Homologues: Orthologues: chimpanzee ZNF821 (100% identical), macaque ZNF821 (99% identical), rabbit ZNF821 (98% identical), pig ZNF821 (98% identical), guinea pig ZNF821 (97% identical), mouse Zfp821 (96% identical), rat Zfp821 (95% identical), dog ZNF821 (72% identical), tropical clawed frog znf821 (70% identical), zebrafish znf821 (50% identical), Drosophila melanogaster CG14440 (17% identical), Drosophila melanogaster CG14442 (17% identical). Paralogues in human: IKZF1 (17% identical), IKZF2 (15% identical), IKZF3 (15% identical), IKZF4 (15% identical), ZNF649 (14% identical), ZNF613 (13% identical), ZNF350 (13% identical), ZNF567 (13% identical), ZNF382 (12% identical), ZNF639 (12% identical), ZNF564 (9% identical).
Diseases named in the same sentence as ZNF821 in open-access papers:
ZNF821 is named in the same sentence as 2 diseases in open-access papers, as found by Europe PMC text mining. Sharing a sentence is not in itself a finding about the gene and the disease. The quoted sentences say what the papers report.
psychosis (1 paper, 2016). "Of these validated MAP biomarkers, four were previously reportedto predict psychosis in an independent human blood transcriptomeinvestigation (FBP1, ZNF821, TBC1D2 andSIN3A), one of which was previously labelled a genetic variantfor SCZ risk (FBP1)." (PMID 27163203, 2016).
ZNF821 also shares sentences with these, for which no sentence is quoted: tumor (1 paper).